MYC (MYC proto-oncogene, bHLH transcription factor)
Diseases named in the same sentence as MYC in open-access papers (continued):
Sharing a sentence is not in itself a finding about the gene and the disease.
cancer (continued). "In total, FISH results on both 6q15 deletions and alterations of HER2, CCND1, MYC, MDM2, PTEN, 8p21, and 9p21 were available in subsets of 921 (HER2), 1007 (CCND1), 699 (MYC), 1022 (MDM2), 980 (PTEN), 986 (8p21), and 902 (9p21) cancers." (PMID 34625909, 2022). "pERK plays critical roles in cell cycle progression via c-MYC stabilization, EMT via ZEB1 induction, apoptosis, autocrine cytokine loops, cancer metabolism, and protein translation." (PMID 35659728, 2022). "c-MYC, a downstream target of ERK5, is involved in EMT, cancer progression and poor patient survival." (PMID 35625825, 2022). "One classic example is the transcription factor and proto-oncogene MYC, which is upregulated in RAS-dependent cancers, where it has been shown to promote different aspects of cancer progression." (PMID 36581205, 2022). "AKT1, MYC, and MAPK are just a few of the cancer-related genes that are impacted by H3K4 methylation." (PMID 36551330, 2022). "The human CD44/MYC-high cluster expressed CENPK and CENPN, which regulate the cell cycle and cell division in cancer." (PMID 35611554, 2022). "Surprisingly, inhibition of CDK9 by a small molecule inhibitor, i-CDK9, enhances MYC expression and only simultaneous inhibition of CDK9 and BRD4 can efficiently induce growth arrest and apoptosis in cancer cells." (PMID 35053227, 2022). "The oncogenic transcription factor c-MYC (MYC) is highly conserved across species and is frequently overexpressed or dysregulated in human cancers." (PMID 35741402, 2022). "Increased levels of this oncogene in normal cells results in apoptosis, whereas in cancers cells, both the XBP1s and IRE1 allow for the cells to avoid an MYC-related cell death." (PMID 36230792, 2022). "Previous studies have demonstrated that both PRMT5 and MSI2 maintain c-MYC expression in cancer cells through independent mechanisms, but we found MSI2 and PRMT5 cooperate by retaining c-MYC translation." (PMID 36167829, 2022). "JQ1 has been proven to be a first-in-class BETi, which can downregulate the transcription of multiple genes through targeting BRD4, such as MYC, IL7R, and E2F1 in different cancer cells." (PMID 36499487, 2022). "Secondly, GSEA indicated that KCDEGs were enriched in several cancer hallmarks such as EMT, MYC targets, KRAS signaling, and inflammatory response." (PMID 35479936, 2022). "The expression of MYC, NR5A2, and SNAI1 was also higher in EC-adjacent tissues than in samples from cancer-free patients." (PMID 36140779, 2022). "By contrast, in vitro studies have identified alterations in MYC, mTOR, and PIK3CA, but notably rarely KRAS alterations, as potential drivers of resistance in MET-addicted cancer cells with MET-amp." (PMID 35326531, 2022). "Emerging evidence shows that cancer cells can acquire super-enhancers in the vicinity of key oncogenes, such as MYC and TAL1, during the development of cancer." (PMID 35300417, 2022). "These processes are regulated by several key transcription factors involved in cancer stemness and sphere formation, such as OCT4, Nanog, SOX2, KLF4, and MYC." (PMID 35912234, 2022). "Thus, we next explored whether miR-138-mediated regulation of MYC extended to other cancers." (PMID 34937878, 2022). "In particular, cluster 11 had high expression levels of cancer stem cell (CSC) marker genes, including NOTCH1, KLF4, CD44, EPAS1, and MYC." (PMID 36618022, 2022).
cancer (continued). "Among them, MYC and WNT/BETA-CATENIN signaling pathways are important regulatory pathways for cancer stem cell self-renewal." (PMID 35784532, 2022). "Previous studies reported that METTL3 and 14 act as oncogenes in several types of cancer by regulating DRG1 and MYC, respectively." (PMID 35794212, 2022). "Moderate levels of MYC/PGC‐1α prompted a plastic phenotype, an intermediate state between differentiated cancer cells and CSCs." (PMID 35386842, 2022). "As well as with oncogene expression, the decrease in MYC expression at 100 μg/mL, in TYMS at 500 μg/mL, and in MDM2 at 250 μg/mL was significantly lower than MTX as a commercial cancer drug." (PMID 35529172, 2022). "Amplified CCT expression in cancer cells could, therefore, directly promote cell cycling by folding essential substrates like tubulin or cdc20 and indirectly through interactions with transcription factors like MYC, and promoting the expression of cell cycling factors like cyclin D." (PMID 35602608, 2022). "Moreover, suppression of MTBP expression in malignant cells or expression of a mutant with apparent dominant-negative activity demonstrated MTBP-directed therapeutics could have broad applicability as cancer therapies and extending patient survival, similar to its binding partner MYC." (PMID 35741402, 2022). "It has been reported that oncogenes such as MYC and KRAS can regulate immune response by suppressing IFN‐I pathways in various cancers." (PMID 35253368, 2022). "Gene group 2 shows an association with pathways including cellular senescence, B-cell receptor signaling, pathways in cancer, transcriptional misregulation, JAK/STAT signaling, E2F targets, and MYC targets." (PMID 35626705, 2022). "This duplication also recurrently affected known cancer census genes such as CSMD3, COX6C, EXT1, FAM135B, MYC, and NDRG1 in SG1 and SG3 in more than 75% of patients." (PMID 36129940, 2022). "Previously, the MYC inhibitor, MYCMI-6 was also found to reduce cell proliferation in a diverse range of cancer cell lines." (PMID 35908121, 2022). "Moreover, CDK12 inhibition may induce the synthetic lethality phenomenon in MYC-dependent cancers." (PMID 35408915, 2022). "According to data obtained by qRT-PCR analysis in cultured cancer and immortalized cells of different types, PSM-induced down-regulation of c-MYC expression varies depending on the cell line." (PMID 36012470, 2022). "MYC binds to DHX33 and promotes PLAU transcription by directly binding to their promoters, thus promoting cancer cell migration." (PMID 35069971, 2022). "Cellular inhibitor of protein phosphatase 2A, by inhibiting protein phosphatase 2A, helps to maintain MYC phosphorylation at Ser 62, thereby ensuring its cooperation with oncogenic KRAS in driving cancer progression." (PMID 36581205, 2022). "It has been reported that MYC helps cells survive under low-oxygen conditions, and emerging evidence suggests that MYC and HIF also cooperate to promote cancer cell growth and progression." (PMID 36359803, 2022). "Some TFs with cancer-related biological functions also showed high Jaccard scores with G4-II, such as E2F6, IRF1, and MYC." (PMID 36092921, 2022). "MYC prevention through a BET inhibitor augmented PGC‐1α expression, engendering the stemness of cancer cells that can be further killed by metformin." (PMID 35386842, 2022).
cancer (continued). "Further we found that CSFs in each developing organ, as well as the corresponding cancer, were likely regulated by FOX (FOXM1), MYC, and BRD family of transcriptional regulators." (PMID 36509773, 2022). "In many cancers, c-MYC acts as an oncogene, and elevated c-MYC levels contribute to transcriptional deregulation." (PMID 35159073, 2022). "Meanwhile, we found that MYC and POU5F1B were co-amplified with EXOSC4 at a high frequency but co-expressed with low correlation in all nine cancer types." (PMID 35008922, 2022). "Relative expression level showed that stromal fibroblasts from both normal and cancer donors promoted upregulation of stemness-related genes (ALDH1, AXIN2, CD133, MYC, and SOX9) in EEC organoids." (PMID 36273006, 2022). "USP29 stabilizes oncogenic MYC (including c-MYC and N-MYC) and hypoxia-induced factor 1α (HIF1α), which are two major drivers of cancer metabolism in normoxia and hypoxia, respectively, by direct interaction and deubiquitination." (PMID 35307036, 2022). "MYC, CCNE1, TERT, KRAS and genes from the PI3K/AKT/mTOR pathway (e.g. PIK3CA) are amongst the commonest amplified cancer genes in HGSOC2,9–13." (PMID 36289203, 2022). "REST target genes upregulated in ER- or TNBCs include MYC, LIF, and EGFR which play significant roles in cancer progression, cell proliferation and endocrine resistance." (PMID 35177031, 2022). "MYC actively represses ZNF148 expression, and in turn, the depletion of ZNF148 leads to de-repression of ID1/3, which drives the cancer stem cell phenotype." (PMID 36207293, 2022). "In colorectal cancer, circ3823 functioned as a ceRNA of miR-30c-5p, alleviating the repressive effect of miR-30c-5p on TCF7 which upregulated MYC and CCND1 and eventually led to cancer initiation and metastasis." (PMID 35081965, 2022). "For example, MYC- and KRAS-driven cancers have been reported to be particularly sensitive to the inhibitors of the key players of lipid and glucose metabolism due to the oncogenic reprogramming of the cellular metabolic pathways." (PMID 36480552, 2022). "DNA methylation of these MYC enhancer docking site with dCas9-DNMT3A-3L protein and specific gRNA reduced MYC expression in K562 and HCT-116 cancer cell lines, possibly due to abrogation of CTCF binding upon methylation." (PMID 35740532, 2022). "For example, сo-duplication of well-known oncogene MYC and its super-enhancers located near strong TAD boundary is often found in different cancer types and accompanied by MYC overexpression." (PMID 36468037, 2022). "Considering that the MYC family plays a key role in regulating cancer metabolism and cell death/survival, exploiting the link between MYC and metabolic cell death pathways, such as ferroptosis, might provide new approaches in treating cancers with aberrant MYC expression." (PMID 35908258, 2022). "The connections between MYC, POLR3G, and cell proliferation and cancer raise important questions about the significance of POLR3G-enhanced transcription, generally, and the functional activities of snaR-A ncRNA, specifically." (PMID 35637192, 2022). "Stem-cell-related pluripotency genes, such as OCT4, SOX2, KLF4, MYC, LIN28, and NANOG, are expressed in various types of cancer cells." (PMID 34488885, 2021).
cancer (continued). "Oncogenic expression of the MYC family members (e.g., MYC and MYCN) drives many human cancers;1 however, strategies aiming at chemically disrupting their functions have proven difficult to develop." (PMID 34183658, 2021). "Notably, while MYC is expressed in a variety of tumors, the lncRNAs are endowed with cell- and cancer type-specific expression which suggests that the same oncogene MYC may influence the expression of distinct sets of lncRNAs, depending on the pathological context." (PMID 34359754, 2021). "Specifically, the oncogenic proteins RAS, MYC, and BRAF have been shown to directly stimulate metabolic pathways by increasing the expression of key metabolic enzymes in cancer cells." (PMID 33766731, 2021). "Indirect targeting of MYCN using small molecule inhibitors such as bromodomain inhibitors and inhibitors that disrupt the interaction between MYC and its binding partner, MAX has been explored in different cancers." (PMID 34680394, 2021). "Enforced expression of GATA3 in HCT116 cells inhibited a series of cancer-promoting proteins, DNMT1, SETD1A, SETDB1, FOXM1, MYC, and MSI1." (PMID 34595169, 2021). "The strong connection of MYC activity and the UPR is also documented across species and cancer entities, explaining increased sensitivity to perturbations in protein homeostasis." (PMID 34637026, 2021). "This interplay between CCAT2, MYC, and WNT molecules has been explored and confirmed in multiple cancers in recent years and is responsible for the main pro-tumorigenic roles of CCAT2." (PMID 34830370, 2021). "Exosomal miR-17-5p secreted by CAFs targets RUNX3 in cancer cells, which enables MYC to activate the transcription of TGF-β1 to promote metastasis and, in turn, activate fibroblasts, forming a cancer positive feedback loop." (PMID 34572947, 2021). "Interestingly, we found gene sets representing MYC targets enriched in Panc1 cells when grown in heterospheroids, indicating that MYC might be a driver of this shift towards a more aggressive cancer subtype." (PMID 33946033, 2021). "The oncoproteins, MYCN, MYC, and MYCL are short-lived transcription factors that are overexpressed or deregulated in more than half of all human cancer, making them attractive therapeutic targets." (PMID 33658627, 2021). "Cluster 7 included cells with aberrant neuronal identity that expressed neuronal development genes (NEFM, DCX, STMN2, HES6) but also cell cycle and cancer-related genes (CRABP2, CCND1, MYC)." (PMID 33771987, 2021). "Among the 4 cancer types, ASB16-AS1 expression in the HIPPO and MYC signaling pathway altered group was significantly." (PMID 34709970, 2021). "NRF2 can promote the survival of detached cancer cells by affecting oncogenes such as RAS, RAF, and MYC." (PMID 34830801, 2021). "Based on the 2^-(ddCt) for TERC/GAPDH and MYC/GAPDH from the controls in Group 2, the threshold of cancer detection for these markers was set at 3.12 and 0.155 respectively." (PMID 34790573, 2021). "Increased TERT mRNA levels were observed after overexpression of SMYD3, while its suppression led to reduced H3K4 trimethylation within the TERT core promoter and also decreased the ability of MYC and SP1 to bind the promoter in cancer cell lines." (PMID 33802026, 2021). "As well-described for c-MYC, both IKZF1 and IRF4 are involved in the development of cancer, including CRC." (PMID 33478584, 2021). "We also observed amplifications of canonical cancer genes, including CCNE1 on 19q12 and MYC on 8q24." (PMID 34145257, 2021).
cancer (continued). "Cells in cluster 5 resembled those in cluster 7 of DNs, and included cells with aberrant neuronal identity that expressed neuronal genes (GAP43, NEFM, DCX, HES6) and cancer-related proliferative genes (CRABP1, MYC, SFRP1)." (PMID 33771987, 2021). "The first has been proven to be necessary for the survival of MYC-driven cancers, whereas several studies have confirmed the role of MUC16 in cancer progression." (PMID 34683922, 2021). "As MYC is often amplified in cancers, concomitant increase in the antiapoptotic BCL2 family often accompanies high levels of MYC activity, facilitating survival in the face of too much MYC." (PMID 34283054, 2021). "The inhibition of hTERT was also linked to the impact of SFN on the expression of MAD1 (a repressor of hTERT) and c-MYC (an activator of hTERT) in MCF-7 and MDA-MB-231 cancer cells." (PMID 34835969, 2021). "The PPI network also indicated that AKT1 and MYC are two hub proteins for cancer progression and metastasis, and the Western blot analysis of AKT activation and MYC expression was employed to reconfirm these prediction data." (PMID 34944720, 2021). "Protein tyrosine phosphatase receptor type S (PTPRS) was highly expressed in OV cancer cells and correlated with MYC/E2F targets, indicating that pleiotrophin (PTN) was secreted by fibroblasts binding to its receptor to promote the cancer cell growth." (PMID 34676217, 2021). "Given the importance of MYC and BCL-2 proteins in cancer, it is unsurprising that there has been considerable interest in the discovery of drugs that can target both these proteins." (PMID 33799592, 2021). "We recently published transcriptomic data on four different cancer types, wherein 11 out of 12 individual CSC populations showed MYC expression and thus emphasizes the overall presence of MYC in CSCs." (PMID 34445612, 2021). "Meanwhile, DDX39 was found to be correlated with hallmarks (such as MYC, G2M, E2F, TGF-β and TNF-α) that participate in cancer activation and cycle acceleration." (PMID 34421357, 2021). "Transcriptome analysis of USO1-depleted SEM cells in our study demonstrated a mixed picture, with the downregulation of certain cancer and cell growth-related pathways, including mTOR and ERB2, but concurrent downregulation of RNA metabolism and MYC targets." (PMID 34162911, 2021). "We then assessed the correlation between MYC expression and 225 metabolites in SCLC using data generated by the Cancer Cell Line Encyclopedia (CCLE)." (PMID 34556188, 2021). "Consistent with this notion, HSP90 inhibitors 17-AAG and PU-H71 have been shown to reduce MYC and AKT protein levels and expression of their target genes in cancer cells." (PMID 33391515, 2021). "Beta-catenin and c-MYC promote the expression of TERT, which in turn interacts back with these oncogenic drivers, to regulate the expression of cancer-specific genes in what appears to be a feed-forward loop." (PMID 33599797, 2021). "Inhibition of HDAC2 by SAHA was able to downregulate MYC and to reactivate TBP-2 expression, blocking cell growth and inducing apoptosis in many cancer cell lines." (PMID 33801599, 2021). "Previous work has shown that c‐MYC increases labile cellular iron availability by repressing FTH1 expression and reducing iron‐storing potential in cancer cells." (PMID 34551213, 2021).